AFP (alpha fetoprotein)
Diseases named in the same sentence as AFP in open-access papers (continued):
Sharing a sentence is not in itself a finding about the gene and the disease.
tumor (continued). "In addition, AFP has been proven to promote tumor proliferation through the initiation of the cyclic AMP-protein kinase A pathway, Ca2+ influx and apoptotic signal transduction mediated by caspase‐3150-152." (PMID 35002508, 2022). "Moreover, patients with high tumor burden (number and size of liver lesions, and AFP levels) were less likely to receive LT/LR/ABL as the first therapeutic option." (PMID 35174092, 2022). "Carfilzomib can effectively inhibit FOXM1 expression to inhibit tumor growth and could be a novel therapeutic option in patients with AFP-positive HCC who receive anti-VEGFR2 antibodies." (PMID 35955438, 2022). "Using a cut-off value of 200 ng/mL for AFP and 1.1 for the tumor-to-normal liver ratio maximum SUV value (SUVmax T/L ratio) to define “high-risk” HCC, they found that the rate of MVI and poor differentiation was 33% and 92%, respectively, in the high-risk group." (PMID 35053580, 2022). "A tumor marker AFP value ≥ 400ug/L was present in 11 patients." (PMID 35223467, 2022). "On multivariable analysis, the post-operative detection of CTCs was the most significant prognostic factor of recurrence (hazard ratio [HR], 2.67; 95% confidence interval [CI], 1.51–4.74; p = 0.001), outperforming variables such as tumor size, number, vascular invasion, and AFP level." (PMID 36033451, 2022). "In 2012, Duvoux reported an AFP model scored by the tumor diameter, number, and AFP level." (PMID 35053580, 2022). "However, alpha-fetoprotein (AFP) remains the primary tumor marker for HCC; its sensitivity and predictive values range from 25–65%." (PMID 36613653, 2022). "The risk factors for HCC recurrence in univariate analysis were; AFP >400 ng/mL (P = 0.01), neutrophil/lymphocyte ratio ≥4 (P = 0.03), moderate/poor differentiated tumor (P = 0.01), pathological tumor grades III and IV (P = 0.03), and microvascular invasion (P = 0.01)." (PMID 36268362, 2022). "A low tumour stage, the absence of vascular infiltration and AFP values within the normal range are associated with improved overall survival." (PMID 36233670, 2022). "Other series have focused on an AFP limit of <400 ng/ml and found a low 5-year recurrence rate of 4.9% in patients with a total tumor diameter of <8 cm, or a 4-year recurrence rate of 9.4% in patients with a total tumor volume (TTV) of <115 cm3 and AFP <400 ng/ml." (PMID 35529597, 2022). "The significance of ΔLDH threshold effect on OS was also considerable (P = 0.021) after adjusting for potential influencing factors including age, sex, WBC, Hgb, PS score, main tumor diameter, Child–Pugh class, location of pathological changes, AFP, and the of intrahepatic pathological changes." (PMID 35710505, 2022). "Combining reduced tumor stiffness and elevated AFP level may provide potentially valuable biomarker for GPC3-targeted immunotherapy." (PMID 36518314, 2022). "Additional tumor marker analysis revealed that the dog tumors did not lead to elevated expression of alpha-fetoprotein, which is a marker associated with HCC in mice that occurs after AAV vector integration." (PMID 35690906, 2022). "RETREAT stratifies 5-year recurrence risk from < 3% in patients without viable tumor or vascular invasion on explant and AFP ≤ 20 ng/mL (i.e. RETREAT score of 0) up to 75% in the highest risk patients (RETREAT ≥ 5)." (PMID 35142988, 2022). "Several clinical risk factors, using conventional Cox proportional hazards regression, have been identified to predict HCC recurrence, including maximum tumor diameter, tumor number, tumor differentiation, macrovascular invasion, serum alpha-fetoprotein (AFP) level." (PMID 35352293, 2022). "Studies have found that NASH-related HCC patients have lower levels of AFP and have hypothesized that this may suggest a less aggressive tumor biology." (PMID 35865863, 2022). "Importantly, complete tumor eradication was achieved in orthotopic HCC mice when AFP212 was replaced with the full-length AFP to form DEXP47&AFP&N1ND (DEXP&A&N) vaccines." (PMID 35488312, 2022).
tumor (continued). "Tumor biomarkers, including AFP, CA125, CA199, CA724, and CEA, were normal in all patients." (PMID 35155220, 2022). "Cox multivariate analysis found that AFP > 400 ng/ml, low ZNF334 expression and MVI were independent risk factors that affected the patients’ OS; while AFP > 400 ng/ml, low ZNF334 expression and portal vein tumor thrombus were the independent risk factors that affected patients’ RFS." (PMID 35534462, 2022). "Likewise, the Asan Medical Center in South Korea also advocated the importance of two tumor markers (AFP < 150 ng/mL and PIVKA-II < 100 mAU/mL)." (PMID 35053580, 2022). "However, patients are typically excluded from transplants based on specific criteria, including tumor size/number and elevated alpha-fetoprotein." (PMID 35565184, 2022). "Similarly, risk factors for RHCC with open LR followed by LT were determined to be elevated AFP levels, microvascular invasion, tumor grade, and multinodular tumors." (PMID 35965558, 2022). "Serum tumor marker alpha-fetoprotein (AFP) is another tool widely used for HCC detection." (PMID 35351916, 2022). "However, in this study, the tumor markers including AFP, CEA, CA 19-9, and CA 125 were elevated in 9 patients." (PMID 35295996, 2022). "Serum tumour markers like alpha-fetoprotein (AFP) are within normal limits." (PMID 36225445, 2022). "Serum AFP is frequently used not only for diagnosis, but also as a predictor of treatment response in clinical practice because it is thought to consistently reflect tumor burden and activity." (PMID 35435327, 2022). "The AFP vaccine presents the AFP epitope polypeptides to antigen presenting cells (APCs), generating multiple AFP-specific cytotoxic T lymphocytes (CTLs) to induce tumor immunity." (PMID 35002508, 2022). "Elevated AFP represents a subgroup in HCC tumor heterogeneity." (PMID 36140381, 2022). "Liver transplant recipients demonstrating a decrease in AFP after treatment, but not yet normalized AFP values prior to liver transplantation have shown an increased risk of tumor recurrence as well." (PMID 35619164, 2022). "In addition, considering the fact that all intracellular antigens are presented by MHC class I molecules, the researcher generated some unique CAR T-cells that particularly bound to AFP 158–166 peptide-MHC complex lysing HLA-A*02:01+AFP+ tumor cells." (PMID 36613878, 2022). "Additionally, multivariate Cox regression suggested that tumor-related characteristics, such as AFP of > 1000 ng/mL, tumor numbers, and maximal tumor diameter, were the independent risk factors for recurrence." (PMID 35936699, 2022). "Tumor marker reduction (AFP or DCP) was observed in 81.4% (96/118 patients)." (PMID 36207618, 2022). "A large US experience including 3,276 patients validated the Risk Estimation of Tumor Recurrence After Transplant (RETREAT) score, consisting of AFP value at LT, microvascular invasion, and the sum of the largest viable tumor and number of tumors in the total hepatectomy specimen." (PMID 35574299, 2022). "In July 2019, tumor biomarkers showed an increase of alpha fetoprotein (AFP) to 27.9 ng/ml." (PMID 35265635, 2022). "For OS, univariate analysis showed that ECOG scores, line of apatinib, AFP, tumor progression, PVTT, and combination therapy may have impacts on it." (PMID 35656302, 2022). "Unfortunately, high-risk patients have poor prognoses, including those with large tumor masses, older children (≥ 8 years old) and those with tumor metastasis or low concentrations of AFP (α fetoprotein ≤ 100 ng/mL) at diagnosis, and there is considerable room for improvement regarding outcomes." (PMID 35986847, 2022). "Furthermore, the cases with the highest serum AFP levels (> 400 ng/dL) in the current study was significantly associated with poor HCC prognostic parameters, large tumor sizes, late stage, and early HCC recurrence." (PMID 36117166, 2022).
tumor (continued). "In all, these data clearly demonstrate the close association of serum-marker expressions with tumour bulk, and this result is consistent with the finding of higher serum levels of bHCG and AFP in patients with larger primary tumours than in those with smaller ones." (PMID 36358866, 2022). "As DKK-1 expression correlated positively with that of AFP in tumors and is involved in angiogenesis in the tumor microenvironment, serum AFP may be a surrogate marker of DKK-1, which facilitates angiogenesis in HCC." (PMID 35269944, 2022). "Univariate analysis showed that Eastern Cooperative Oncology Group (ECOG) scores (p <0.05), line of apatinib (p <0.001), AFP (p <0.001), tumor progression (p <0.05), PVTT (p <0.05), and combination therapy (p <0.001) may impact the OS." (PMID 35656302, 2022). "Univariate analysis showed that line of apatinib (The lines of apatinib treatment), AFP, tumor progression, portal vein tumor thrombus (PVTT), and combination therapy may impact the PFS of patients." (PMID 35656302, 2022). "Therefore, it is necessary to apply adjuvant sorafenib to facilitate RFA in patients with M1 along with a tumor size of 3–5 cm, tumor number of two to three, or AFP >400 μg/L." (PMID 35814378, 2022). "Furthermore, the correlation between c-Met and serum tumor markers (AFP, CEA, CA199, CA153, CA125, CA50) in GC progression was discussed." (PMID 35710379, 2022). "The level of AFP in blood is related to the size of HCC tumor." (PMID 35464224, 2022). "In summary, despite having a higher tumor burden, higher level of AFP, larger proportion of patients with Child-Puge grade B, ECOG PS 2, PVTT, and extrahepatic metastasis, the studies confirmed superior PFS, OS, or ORR compared with Phase Ib Study and the IMbrave150 trial." (PMID 36249023, 2022). "These criteria are applied to pre-operative imaging +/- serum alpha-fetoprotein (AFP) levels to determine LT eligibility and may differ from the eventual explant pathology (i.e., underestimate tumor stage) in 15-30% of patients." (PMID 36387254, 2022). "The reason may be that laboratory tests can provide additional predictive information independent of imaging, such as the function of tumors to secrete AFP, liver function, or tumor function information reflected by GGT." (PMID 37850181, 2022). "Other independent prognostic factors included AFP, PLR, SII, CSPH, tumor size and blood loss." (PMID 35606690, 2022). "Notably, three metabolic clusters were identified by unsupervised clustering analysis, and high levels of FFAs in tumor tissues were the key characteristics of the cluster with poor prognosis, accompanied by a high level of AFP." (PMID 35008393, 2022). "Several studies developed clinical models based on some clinical risk factors including tumor number, size, and alpha-fetoprotein (AFP) to predict MVI status (AUC not exceeding 0.81)." (PMID 35875110, 2022). "Furthermore, four serum tumor biomarkers (i.e., AFP, CEA, CA-125, and CA-199) in the digestive system seem to be unable to discern between controls and GCs." (PMID 35572666, 2022). "Finally, the RETREAT score, which has been validated nationally (including in patients requiring tumor down-staging) incorporates AFP at LT, vascular invasion, and the sum of the largest viable tumor diameter (in cm) and number of viable tumors on explant." (PMID 35142988, 2022). "In addition to serial evaluation by MRI to look for imaging characteristics consistent with tumor viability, AFP trajectory has been used to evaluate response to therapy." (PMID 36290870, 2022). "With the continuous advances in molecular medicine, a new chapter in this domain has been opened and the research of newer, stronger biomarkers associated with HCC is a must, especially for AFP-negative tumours." (PMID 35497085, 2022).
tumor (continued). "Among the HCC patients with normal preoperative AFP levels or without MVI, however, the median VAF in baseline ctDNA > 1% maintained good predictive performance for early tumor recurrence (HR, 5.4; P = 0.041 for the AFP normal group and HR, 18.3; P = 0.047 for non‐MVI group, respectively)." (PMID 34543520, 2022). "Multivariate logistic regression analysis showed that inflammatory score (OR = 2.14, 95% CI: 1.63–2.88, p < 0.001), alpha fetoprotein (OR = 2.02, 95% CI: 1.46–2.82, p < 0.001), and tumor size (OR = 2.37, 95% CI: 1.70–3.30, p < 0.001) were independent factors for MVI." (PMID 35310437, 2022). "In addition, enhanced expression of this protein is positively correlated with elevated concentrations of the classical tumour marker for HCC—alpha-fetoprotein (AFP), tumour stage and size, histological differentiation, tumour recurrence and tumour metastasis." (PMID 35565436, 2022). "Biologically, AFP promotes tumour proliferation and portends to poor prognosis." (PMID 35158772, 2022). "Another limitation was the unavailability of serum tumor markers (alpha-fetoprotein, human chorionic gonadotropin, and lactate dehydrogenase), nor did it include methods of treatment which might have shown the effectiveness of the treatment modalities." (PMID 36353476, 2022). "T cells could suppress HLA-A*02:01+/AFP+ tumor growth in vivo and in vitro after being transduced by this AFP-CAR." (PMID 35002508, 2022). "Importantly, the effects of high tacrolimus IPV on HCC recurrence remained significant in the fully adjusted model accounting for differences in tumor number, tumor size, microvascular invasion, AFP level, and mean tacrolimus trough concentration." (PMID 36171260, 2022). "Multivariate analyses showed that the MobileNetV2_HCC_class had an independent prognostic value (HR = 3.44 (2.01–5.87), p < 0.001) after adjusting known prognostic markers remarkable in the univariable analyses, such as Stage AJCC, AFP, tumor number, and tumor size." (PMID 35352293, 2022). "AFP also tightly coexists with large tumor burden, and predicts decreased survival in HCC patients." (PMID 35158917, 2022). "AFP is the widely used tumor marker for PLC, especially for the HCC-containing tumors." (PMID 35242699, 2022). "Moreover, Cox univariate survival analysis showed that HCC patients with tumor size > 5.6 cm, advance tumor stage (T4/T3/T2), AFP > 25 ng/ml, ALT > 25U/L, or AST > 60U/L significantly associated with worse OS." (PMID 35093119, 2022). "In HCC, several miRNAs, including miR-10b, miR-21, miR-122, and miR-200a, may serve in conjunction as promising tumour markers complementary to α-fetoprotein (AFP) for the diagnosis of early-stage HCC." (PMID 36167539, 2022). "As for the prognostic risk factors, various clinicopathological risk factors, including AFP level >400 ng/ml, extent of PVTT, and tumor diameter >5 cm, and almost all risk factors related to HCC patient prognosis, were related to actual long-term survival in a Chinese nationwide study." (PMID 36420403, 2022). "Because of the presence of mesenteric adenopathy and concern about a malignant process, tests for tumor markers revealed a mildly elevated CA-125 at 199.5 units/mL (normal range 0–35 units/mL) and an elevated alpha fetoprotein (AFP) at 13.67 ng/mL (normal range 0–5.63 ng/mL)." (PMID 36340021, 2022). "In addition to expression of the hub genes, we noticed that GPC3 and IGF2 were expressed in 65–75% and AFP in more than 40% of the tumour samples." (PMID 36345011, 2022). "Univariable and multivariable logistic regression analysis firstly identified tumor c (odds ratio [OR], 0.361; 95% CI: 0.158, 0.826; P = 0.02) and serum AFP levels over 20 ng/mL (OR, 8.117; 95% CI: 2.422, 27.199; P = 0.001) as two independent predictors of GPC3-positive HCCs." (PMID 36518314, 2022).
tumor (continued). "According to the results of multivariate COX regression analysis of the model group, 9 predictors including age, tumor size, pathological grade, AFP, radiation, chemotherapy, AJCC stages and surgery were included in the nomogram model that predicted the prognosis of MVI in HCC patients." (PMID 36185206, 2022). "AFP, as a tumor marker, is widely used for the diagnosis of HCC." (PMID 35637856, 2022). "An AFP-derived peptide-loaded DC vaccine could promote an AFP-specific anti-tumor immune response in patients with HCC, and the clinical trial results showed these vaccine-induced CD8+ T-cell responses." (PMID 35619702, 2022). "Both DSMs-TACE with 50 ± 7 μm microspheres 300-500 μm DEB-TACE are effective for local control for HCC, but our findings revealed superiority of the first method over the second in terms of initial (one month) biological (serum AFP levels) and radiological tumor response to treatment." (PMID 35434518, 2022). "In the retrospective study of 132 HCC patients who received TACE + RFA, tumor size, combined portal venous collateral circulation, alpha-fetoprotein, total bilirubin, and Child–Pugh grade are found to be independent risk factors that affect OS and the overall coexistence rate." (PMID 35898584, 2022). "Univariate analysis showed that the hardness of tumor-adjacent tissues (P = 0.003), elastic strain rate ratio (P = 0.032), maximum tumor diameter (P < 0.001), and alpha-fetoprotein (AFP) level (P = 0.007) was significantly different in the patients with and without microvascular invasion." (PMID 35562688, 2022). "A higher CEBPA-DT expression level was significantly correlated to more elevated serum Alpha-fetoprotein (AFP) level, larger tumor size, poor tumor differentiation and microvascular invasion (MVI), suggesting that higher CEBPA-DT expression was associated with HCC growth and metastasis." (PMID 36471363, 2022). "Tumor marker examination revealed normal levels of serum AFP (<20.0 ng/mL) in all patients." (PMID 35231071, 2022). "Moreover, Gal-1 positively correlates tumor markers, such as AFP and CA 19-9 and with tumor histological differentiation stage." (PMID 35611243, 2022). "AFP and tumor number are significant prognostic factors for RFS." (PMID 36212462, 2022). "We thoroughly investigated the relationship between FGF19-FGFR4-KLB and the clinical pathological information of HCC from the TCGA database, including Overall survival, AFP level, Histologic grade, Pathology stage, Metastasis stage, Tumor stage, Node stage, and Vascular invasion." (PMID 36532586, 2022). "In addition, the levels of tumor markers including alpha-fetoprotein, arginase-1, alpha-L-fucosidase, and ferritin were significantly increased, whereas the hepatic miR-122 level was significantly decreased in induced-HCC rats." (PMID 35081125, 2022). "Among them, the hsa-miR-371a-3p has shown the best clinical results, outperforming the classical serum tumor markers nowadays available in the routine [alpha fetoprotein (AFP), human chorionic gonadotropin (HCG), and lactate dehydrogenase (LDH)], which show important limitations." (PMID 35756620, 2022). "Tumor biomarkers (CK18/PD-L1/EpCAM/AFP) and endothelial cell biomarker CD31 are heterogeneously localized in the cytoplasm, on the nuclear envelope, or in the nuclei, while stem cell biomarker CD133 and mesenchymal cell biomarker Vimentin mainly showed an intracellular distribution." (PMID 35311070, 2022). "Additionally, higher EIF4A3 protein levels were observed in HCC samples from the CPTAC cohort compared to NTAT, associated with lower survival and higher recurrence, and correlated with the number of tumours, alpha‐fetoprotein levels and tumour size." (PMID 36419260, 2022). "In this section we focus on AFP and viral associated peptides as TCR-T HCC tumour targets." (PMID 35158772, 2022).